UXT (ubiquitously expressed prefoldin like chaperone)
Description:
Involved in gene transcription regulation. Acts in concert with the corepressor URI1 to regulate androgen receptor AR-mediated transcription. Together with URI1, associates with chromatin to the NKX3-1 promoter region. Negatively regulates the transcriptional activity of the estrogen receptor ESR1 by inducing its translocation into the cytoplasm. May act as nuclear chaperone that facilitates the formation of the NF-kappa-B enhanceosome and thus positively regulates NF-kappa-B transcription activity. Potential component of mitochondrial-associated LRPPRC, a multidomain organizer that potentially integrates mitochondria and the microtubular cytoskeleton with chromosome remodeling. Increasing concentrations of UXT contributes to progressive aggregation of mitochondria and cell death potentially through its association with LRPPRC. Suppresses cell transformation and it might mediate this function by interaction and inhibition of the biological activity of cell proliferation and survival stimulatory factors like MECOM. [Isoform 1]: Plays a role in protecting cells against TNF-induced apoptosis by preventing the recruitment of FADD and caspase 8 to the apoptotic complex I, composed of TRADD, TRAF2 and RIPK1/RIP.
Synonyms: ART-27; STAP1; SKP2
Tractability: PROTAC: UniProt records ubiquitination sites on it; ubiquitination databases record sites on it.
Gene: Protein-coding gene on chromosome X (47,651,792 to 47,659,187, reverse strand). Ensembl gene ENSG00000126756.
Subcellular location: Cytoplasm (Isoform 1); Nucleus (Isoform 2); Cytoplasm; Nucleus; Cytoplasm, cytoskeleton, microtubule organizing center, centrosome; Cytoplasm, cytoskeleton, spindle pole
Subcellular location (Human Protein Atlas): Basal body; Centriolar satellite
Pathways (Reactome):
Gene expression (Transcription): Transcriptional Regulation by E2F6
Gene Ontology:
Molecular function: actin filament binding; beta-tubulin binding; chromatin binding; protein binding; transcription corepressor activity; microtubule binding
Biological process: centrosome cycle; microtubule cytoskeleton organization; negative regulation of transcription by RNA polymerase II; mitochondrion transport along microtubule; protein stabilization
Cellular component: centrosome; cytoplasm; cytoskeleton; nucleus; RPAP3/R2TP/prefoldin-like complex; chromatin; nucleoplasm; protein folding chaperone complex; spindle pole
Homologues: Orthologues: chimpanzee UXT (100% identical), macaque UXT (100% identical), rabbit UXT (95% identical), guinea pig UXT (94% identical), pig UXT (94% identical), mouse Uxt (91% identical), dog UXT (90% identical), rat Uxt (89% identical), tropical clawed frog uxt (55% identical), zebrafish uxt (55% identical).
Diseases named in the same sentence as UXT in open-access papers:
UXT is named in the same sentence as 20 diseases in open-access papers, as found by Europe PMC text mining. Sharing a sentence is not in itself a finding about the gene and the disease. The quoted sentences say what the papers report.
prostate carcinoma (5 papers, 2013 to 2019). A carcinoma that arises from epithelial cells of the prostate gland. "Loss of UXT expression in primary prostate cancer is positively associated with high Gleason grade and poor relapse-free survival." (PMID 30774773, 2019). "To explore the impact of loss of UXT in CaP, we first surveyed its protein expression in multiple prostate cancer cell lines." (PMID 30774773, 2019). "Analysis of a small clinical cohort suggested that loss of UXT expression in primary prostate cancer may be associated with tumor recurrence and poor prognosis." (PMID 30774773, 2019). "Our findings demonstrate that loss of UXT is an early event during prostate cancer progression, which may contribute to genome instability." (PMID 30774773, 2019). "Altogether our results suggest that loss of UXT in human prostate may promote genome instability in normal prostate epithelial cells and that loss of UXT as an early event in prostate cancer may lead to chromosomal alterations." (PMID 30774773, 2019). "Interestingly, the loss of UXT protein is not limited to advanced prostate cancer, instead, it is commonly found in both BPH and HGPIN." (PMID 30774773, 2019). "Depletion of UXT activates DNA damage checkpoint genes, promotes proliferation, and induces cell resistance to anti-androgen treatment in prostate cancer cells." (PMID 30774773, 2019). "Here we analyzed a tissue microarray consisting of normal prostate, benign prostatic hyperplasia, high grade prostatic intraepithelial neoplasia (HGPIN) and primary prostate cancer cases for UXT protein expression." (PMID 30774773, 2019). "We then used prostate-specific UxtKO transgenic mice and prostate cancer cell culture models to investigate UXT function in CaP development and progression." (PMID 30774773, 2019). "In this study, UXT knockout in prostate cancer cells promoted mRNA expression of both long-interspersed and short-interspersed non-LTR sequences, including LINE-1 and Alu families, respectively." (PMID 30774773, 2019). "Our previous studies showed that UXT regulates transcription repression including androgen receptor (AR) signaling in prostate cancer." (PMID 30774773, 2019). "The much larger patient cohort analysis in the current study clearly demonstrates decreased UXT expression during prostate cancer progression." (PMID 30774773, 2019). "Our previous work identified UXT as a transcription factor that directly binds to the AR N-terminus and modulates AR transcriptional activity in prostate cancer cells." (PMID 30774773, 2019). "Here we analyzed a large clinical cohort of prostate cancer to investigate UXT expression in disease progression." (PMID 30774773, 2019). "Our lab has shown that UXT knockdown reduces URI-1 protein stability in prostate cancer cells." (PMID 29649254, 2018). "Notably, UXT is highly expressed in various tumor tissues, and serves as a co-activator of androgen receptor in prostate cancer." (PMID 25617435, 2015).
cervical carcinoma (1 paper, 2015). A carcinoma arising from either the exocervical squamous epithelium or the endocervical glandular epithelium. "Colocalization between PIAS2 and UXT was identified in the nucleus and cytoplasm of HEK 293T and human cervical carcinoma HeLa cells." (PMID 25434787, 2015).
clear cell renal cell carcinoma (1 paper, 2020). "UXT is a novel regulator of the polycomb repressive complex 2 (PRC2) and acts as a renal cancer oncogene that affects the progression and survival of clear cell renal cell carcinoma patients." (PMID 32606327, 2020).
motor neuron disease (1 paper, 2020). "It has been reported that UXT can interact with Als2, a gene that causes mutations in autosomal recessive forms of motor neuron disease, and the interaction of Als2 and UXT has an important role in the activation of the NF-κB pathway." (PMID 32699605, 2020).
prostate tumors (1 paper, 2019). "Our previous study in a small cohort linked loss of UXT expression in primary prostate tumors with tumor recurrence." (PMID 30774773, 2019).
retina degeneration (1 paper, 2023). "In contrast, conditional knockdown of Uxt (ubiquitously expressed prefoldin like chaperone), a positive regulator of mTOR activity, in the mouse retina resulted in severe retina degeneration resembling that in RP." (PMID 37034386, 2023).
sarcoma (1 paper, 2015). A usually aggressive malignant neoplasm of the soft tissue or bone. "Using a combination of loss-of-function and gain-of-function approach, we provided multiple lines of in vitro and in vivo evidence demonstrating an oncogenic role of UXT in sarcoma progression." (PMID 25974965, 2015). "We thus used sarcoma as a model to show that UXT acts as an oncogene promoting cell proliferation in vitro and tumor progression in vivo." (PMID 25974965, 2015).
tumor (7 papers, 2015 to 2025). "Our report suggested that UXT is a MYC-regulated gene that is highly expressed in GC tissues in early or advanced stages of tumor progression." (PMID 31645899, 2019). "An important aspect is that UXT can interact physically and functionally with transcription factors, and can act as tumor suppressor or oncogene." (PMID 31645899, 2019). "It is intriguing for future studies to explore whether UXT promotes tumor metastasis by potentiating angiogenesis." (PMID 25617435, 2015).
cancer (5 papers, 2013 to 2019). A tumor composed of atypical neoplastic, often pleomorphic cells that invade other tissues. "Our findings in this animal model are consistent with clinical data showing that loss of UXT is an early event during cancer initiation." (PMID 30774773, 2019). "We next used an in vivo mouse model to determine whether loss of UXT in prostate could promote cell proliferation and accelerate cancer progression." (PMID 30774773, 2019). "We found that HGPIN and malignant tumors have significantly decreased UXT expression compared to the normal prostate." (PMID 30774773, 2019). "Although UXT is highly expressed in several types of human cancers, the exact mechanism of its contribution to tumorigenesis and cancer progression is still not understood, and seems to be tissue specific." (PMID 31645899, 2019). "The relevance of UXT/PTEN loss in the development of HGPIN and cancer, and determining if loss of UXT is a driver or passenger of eventual cancer development in a subset of HGPIN patients are important questions that still need to be explored." (PMID 30774773, 2019). "Given the importance of elevated glycolysis, or “Warburg effect” in cancer cell proliferation and survival, the UXT-mediated induction of glycolysis prompted us to examine its role in cell proliferation." (PMID 25974965, 2015). "Low levels of UXT in cancer may also play a role in progression as evidenced by biochemical recurrence and poor relapse-free survival." (PMID 30774773, 2019). "Future studies are also warranted on the genomic instability caused by the loss of UXT, focusing on possible deregulation of UXT interactions with URI, EVI1, and NF-κB, potentially providing cancer cells with a means to evade detection from inflammatory pathways and activation of immune signaling." (PMID 30774773, 2019). "In addition, cancer cells with UXT depletion have increased retrotransposition activity and accumulated DNA damage." (PMID 30774773, 2019). "Our data suggest that loss of UXT expression occurs during HGPIN and remains low in cancer." (PMID 30774773, 2019). "Such an oncogenic role of UXT is consistent with its overexpression in human cancer." (PMID 25974965, 2015). "Consistent with the importance of increased glycolytic metabolism or the Warburg effect in cancer cell proliferation and survival, we demonstrated that UXT expressing cells depended on glycolysis for proliferation and survival, displaying heightened susceptibility to glycolytic inhibition." (PMID 25974965, 2015).
neurodegenerative disease (2 papers, 2021 to 2025). A disorder of the central nervous system characterized by gradual and progressive loss of neural tissue and neurologic function. "Based on these results, we propose that UXT may serve as a potential therapeutic target for drugs aimed at treating neurodegenerative diseases associated with protein aggregation, including ALS." (PMID 33782410, 2021). "Based on these results, we suggest that oligomerization-dependent control of UXT function can be utilized as a therapeutic strategy against neurodegenerative diseases and other protein aggregation-related disorders." (PMID 40092611, 2025). "In case of UXT, there are no known mutations associated with neurodegenerative diseases, presumably because functionally harmful mutations in UXT may be lethal as in the Xenopus study, where its knockdown leads to severe developmental defects." (PMID 33782410, 2021).
UXT also shares sentences with these, for which no sentence is quoted: amyotrophic lateral sclerosis (2 papers); benign prostatic hyperplasia (1); breast carcinoma (1); colonic carcinoma (1); colorectal cancer (1); endometrial cancer (1); Gynecomastia (1); hepatocellular carcinoma (1); prostatic intraepithelial neoplasia (1); renal carcinoma (1).